WRN (WRN RecQ like helicase)
Diseases named in the same sentence as WRN in open-access papers (continued):
Sharing a sentence is not in itself a finding about the gene and the disease.
cancer (continued). "Despite the rarity of WS, several common polymorphisms in the WRN gene have been associated with different cancers in specific populations." (PMID 27863399, 2016). "In this study, we identified a novel WRN frameshift mutation in three cancer patients and an unaffected family member using multiplex testing." (PMID 26241669, 2015). "Multiplex genetic testing of 90 cancer predisposition genes revealed WRN frameshift mutations in the three patients." (PMID 26241669, 2015). "A novel WRN frameshift mutation (p.N1370Tfs*23) was identified in the three cancer patients and in the youngest unaffected daughter." (PMID 26241669, 2015). "These two diseases are characterized by a high frequency of cancer predisposition, illustrating the primary importance of WRN and BLM in preventing tumorigenesis." (PMID 25400656, 2014). "There are five members of the RecQ helicases; WRN and RecQ4 are members of the RecQ helicases associated with premature aging and cancer predisposition." (PMID 24620826, 2014). "Because WRN mutations lead to double-stranded DNA damage repair entropy, the increased genomic instability is a cause for concern for any sort of cancer." (PMID 25018888, 2014). "Mutations in three of which including BLM, WRN and RecQL4 have been linked to distinct human disorders with common characteristics of premature aging and cancer predisposition." (PMID 23894508, 2013). "These types of additional analyses have the potential to provide insight into the origins of cancer in WS, and the potential contribution of WRN mutations to cancer risk in the general population." (PMID 23573208, 2013). "The increased risk of cancer in individuals with WS has established the role of WRN as a tumor suppressor gene." (PMID 24308539, 2013). "Generally, we observed the WRN was subject to hemizygous gene loss, a category of genetic aberrations that are increasingly being scrutinized for a specific role in cancer development." (PMID 24308539, 2013). "Werner syndrome is an autosomal recessive disorder associated with premature aging and cancer predisposition caused by mutations of the WRN gene." (PMID 21549004, 2011). "Mutations in three of the five known RecQ family members in humans, BLM, WRN and RecQ4, lead to disorders that are characterized by predisposition to cancer and premature aging." (PMID 19572017, 2009). "The importance of WRN in regulating genome stability is highlighted by the high cancer incidence in WS patients, while epigenetic inactivation of WRN is also associated with human cancer." (PMID 18346216, 2008). "BLM and WRN, human RecQ helicases associated with cancer and disease, have both been shown to associate with duplex telomere repeat binding protein TRF2 in vivo, and BLM co-localizes to telomeric foci exclusively in ALT cells." (PMID 15642092, 2005). "Loss of WRN induces DSBs in MSI cancers and selectively promotes apoptosis and cell cycle arrest." (PMID 39759116, 2025). "Similarly, in BACA2-deficient breast cancer cells, WRN helicase protects against the over-degradation of stalled forks in BRCA2-deficient cancer cells by inhibiting the activity of MRE11 and EXO1 nuclease on the degenerating forks." (PMID 39759116, 2025). "Additionally, WRN has been implicated in synthetic lethality in cancers with microsatellite instability, further demonstrating the importance of these genes in preventing cancer and other diseases." (PMID 40557275, 2025). "Given the autosomal recessive inheritance of the WRN mutation, genetic screening of relatives may help identify carriers and inform them about their cancer risks and potential need for surveillance." (PMID 39958080, 2025). "Due to arguments discussed earlier (i.e., different types of cancers dominating statistically in different species), the dynamics of WRN (the effector mutated) may hold the key to why these cancers appear rarely in humans." (PMID 39796112, 2024).
cancer (continued). "Through mapping cancer type-specific in silico KMT2D GI networks, we revealed several SL candidates, namely NDUFB4, MDM2, TUBA1B, and WRN, that encode targets of existing and in-development therapeutics, making them potentially viable drug targets in cancers harbouring KMT2DLOF alterations." (PMID 39578878, 2024). "Thus, to investigate the role of specific WRN domains in the synthetic lethal interaction with MSI, we used CRISPR base editing to introduce single-nucleotide WRN variants in two MSI cancer cell lines and assessed effects on growth." (PMID 38587317, 2024). "Most studies suggest that WRN is involved in the response to replication stress, although more research is needed to understand the connections between the genome maintenance defects caused by WRN loss and at least the non-cancer phenotypes that are associated with WS." (PMID 39125869, 2024). "For example, Kulminski and Culminskaya reported that subjects with one A allele at the WRN SNP 1133A were associated with an earlier onset of cardiovascular diseases and cancer (and thus decreased longevity) when compared with individuals homozygous for a serine residue (S/S) at this SNP." (PMID 36684006, 2022). "Collectively, our findings identify hitherto unknown non‐enzymatic role of WRN RECQL helicase in pathological mechanisms underlying TOP1cc processing and subsequent NF‐κB‐activation, offering a potential targeted therapy for WRN‐deficient cancer patients." (PMID 35582959, 2022). "Mutation in Werner syndrome protein (WRN) predisposes to cancer." (PMID 35935942, 2022). "The WRN gene, which encodes for a protein with helicase and exonuclease activity involved in genomic integrity, is mutated in Werner syndrome, a form of progeria whose features include early onset cancer." (PMID 36214609, 2022). "In addition to the elevated risk of developing cancer in WS patients, several studies have indicated a tumor suppressor-like function for WRN, while making it a prominent cancer-predisposing gene." (PMID 34164337, 2021). "Thus, the in vivo data are consistent with results from cell-based assays demonstrating preferential killing of BRCA2-deficient cancer cells by WRN helicase inhibition." (PMID 34772932, 2021). "Loss of WRN helicase causes severe genome integrity defects in microsatellite high-instability cancer cells, and this functional impairment might be attributable to defective mismatch repair." (PMID 34943966, 2021). "Importantly, the differential sensitivity of normal and cancer cells to acute WRN depletion points to a vulnerability in cancer cells that renders them more susceptible to WRN inhibitors." (PMID 33054770, 2020). "In cancer, WRN mutations (WRN-mut) lead to genomic instability." (PMID 32455893, 2020). "This metabolic shift is tolerated by normal cells but causes acute oxidative stress overload in rapidly growing cancer cells, which suppresses their proliferation and further analysis suggested that the metabolic changes induced by WRN depletion are caused by attenuated translation." (PMID 33054770, 2020). "WRN is frequently methylated in various cancers, while is rarely mutated." (PMID 32974031, 2020). "Together, these findings suggest a potential role of WRN as regulator of R-loop-associated genomic instability, strengthening the notion that conflicts between replication and transcription can affect DNA replication, leading to human disease and cancer." (PMID 30657978, 2019). "In order to investigate the cellular basis for the viability reduction of MSI-H cancer cells upon WRN depletion, we monitored the consequences of WRN loss-of-function using immunofluorescence analysis of the nuclear membrane protein LAP2β and Hoechst DNA staining in MSS and MSI-H CRC cell lines." (PMID 30910006, 2019). "WRN dependency in MSI-H cancer cell lines is linked to its helicase function." (PMID 30910006, 2019).
cancer (continued). "We assume that elevated expression levels of ATR and WRN might be linked to longevity and cancer resistance in Spalax, given that Heterocephalus also showed higher expression of these two genes." (PMID 29084988, 2017). "Mutations in WRN leads to defects in DNA repair, premature aging and to cancer susceptibility." (PMID 26959889, 2016). "Our results may also serve to guide genomic and population-based analyses of cancer in WRN mutation carriers, and in sporadic cancers of the types most frequently observed in WS." (PMID 23573208, 2013). "Understanding how the WRN deficiency leads to a rapid heritable and sporadic carcinogenesis thus becomes a critical task relevant to the new forms of treatment and prognosis of cancer." (PMID 21267443, 2011). "Our study of silencing WRN in HL60 and TK6 cells suggests that this multistep model may accurately illustrate the etiology of cancer development in WS patients as well as other diseases related to functional loss of WRN (Figure." (PMID 21267443, 2011). "This is of particular importance for tumorigensis as the loss or inactivation of WRN may accelerate the mutation of other critical genes, which would thus enhance the likelihood of cancer." (PMID 21267443, 2011). "WRN has been suggested to be the “caretaker” of the genome, as its absence in WS patients leads to increased genomic instability and predisposition to cancer." (PMID 21267443, 2011). "Furthermore, results from the in silico GI screens identified several SL candidates—namely NDUFB5 (in the STAD screen), MDM2 and TUBA1B (in the COAD/READ screen), and WRN (in the pan-cancer and COAD/READ screens)—which encode proteins that can be inhibited using existing and in-development drugs." (PMID 39578878, 2024). "Thus, identifying WRN deficiency in individual cancer patient may help in achieving better and predictable prognosis through TOP1 inhibitor‐based personalized/targeted therapy." (PMID 35582959, 2022). "Also, study showed that using CHK1 inhibitor in WRN-deficient cancer cells could produce synergic killing effect." (PMID 35855837, 2022). "A number of experimental and computational studies have implicated RECQ helicases – primarily BLM and WRN - as potential targets for cancer therapy, due to the synthetic lethality of their silencing or downregulation with genetic defects inherent in a range of different cancers." (PMID 33647232, 2021). "However, the lower incidence of mutations in genes of the ‘CIN pathway’ in WRN-mut samples could indicate that mutations in WRN play a role in the evolution of these cancers." (PMID 32455893, 2020). "Moreover, somatic WRN mutations are identified in 4% of colorectal tumors and in other cancers." (PMID 32585810, 2020). "In addition to genome instability, which is a hallmark of WS, cancer, and aging, WRN may play an important role in epigenetic maintenance systems, affecting methylation patterns of hundreds of downstream genes." (PMID 31259468, 2019). "WRN is involved in DNA replication, recombination, and repair, and defects in this helicase are a cause of Werner's syndrome, a rare autosomal recessive genetic disorder characterized by premature aging, increased genomic instability, and increased cancer susceptibility." (PMID 27034008, 2016). "The hypothesis defending the link between the methylation-mediated inactivation of WRN and a mutator phenotype in human malignancies is supported by the observation that WRN defective cancer cells through methylation are very sensitive to the action of DNA-damaging agents." (PMID 22778947, 2012). "The findings not only provide pharmacological validation of the synthetic lethality of WRN in cancer, but also provide important information for the development of new cancer treatment strategies." (PMID 40240755, 2025). "In recent years, based on this genomic vulnerability caused by WRN mutations, its targeted inhibitors have achieved surprising synthetic lethal effects in microsatellite instability (MSI) cancers." (PMID 40649870, 2025).
cancer (continued). "Including DNA-PKcs, CHK1, CDK12, RAD51, POLθ and WRN, inhibitors of these pathways can provide new opportunities for cancer treatment by inducing synthetic lethality." (PMID 40240755, 2025). "Given that WRN is a critical anticancer target, the development of a technique to evaluate WRN inhibitors holds significant importance in cancer therapy." (PMID 39737862, 2025). "Among them, the WRN helicase was identified through successful genome‐wide genetic screenings in CCLs and confirmed using different cancer models in subsequent studies." (PMID 39814695, 2025). "The discovery of VVD-214/RO7589831 represents a significantmilestone in the development of WRN inhibitors for the potential treatmentof MSI-H cancers." (PMID 40964743, 2025). "Studies have shown that WRN helicase is abnormally increased in various malignant tumor tissues such as breast cancer, colorectal cancer, and leukemia, which regulates genomic stability to participate in the occurrence and development of tumors." (PMID 40649870, 2025). "Recent studies have demonstrated that WRN activation is critical for the survival of cancer cells characterized by MSI." (PMID 40261911, 2025). "Elucidating the function of the WRN gene holds promise for the development of novel therapeutic approaches, targeting not only WS, but also a wide range of cancers and age‐related disorders." (PMID 40530580, 2025). "Using a genetic screen, the study team discovered that the Werner syndrome RecQ deconjugase WRN is a synthetic lethal target in microsatellite instability (MSI) cancer cells." (PMID 40240755, 2025). "Werner syndrome helicase (WRN) has emerged as a compellingtherapeutictarget for microsatellite instability-high (MSI-H) cancers, owingto its selective dependency on the helicase activity of WRN." (PMID 40964743, 2025). "These inhibitors mimic genetic WRN loss, induce DNA damage, and selectively suppress MSI cancer cell model growth, including in patient-derived organoids, tumour xenografts, and PDX models of immunotherapy-resistant disease." (PMID 38587317, 2024). "Here, we used single-molecule tracking (SMT) in combination with a WRN inhibitor to examine WRN dynamics within the nuclei of living cancer cells." (PMID 39025847, 2024). "The discovery of potent, selective covalent WRN inhibitors provides proof of concept for synthetic-lethal targeting of WRN in MSI cancer and tools to dissect WRN biology." (PMID 38587317, 2024). "Recent work uncovered a synthetic lethal relationship between loss of the WRN RecQ-like helicase and MSI cancers." (PMID 38587317, 2024). "We report the discovery and development of covalent WRN inhibitors, which have potent anti-cancer effects across various MSI models." (PMID 38587317, 2024). "Base editing screens successfully pinpointed critical residues on WRN essential for its synthetic lethality in MSI cancer cells." (PMID 38587317, 2024). "This provides pharmacological proof-of-concept supporting WRN inhibition as a novel therapeutic approach for the treatment of patients with MSI-H cancers, including those resistant to standard-of-care therapies." (PMID 38587317, 2024). "The discovery of WRN-MSI synthetic lethality represents a new opportunity for synthetic lethal-based targeted cancer therapies." (PMID 38587317, 2024). "WRN inhibitor also sensitized cancer cells to the G4 stabilizer telomestatin, consistent with its role in telomere maintenance." (PMID 39125869, 2024). "Efforts to evaluate additional non-colorectal preclinical models would deepen our understanding of sensitivity factors in the setting of MSI and potentially widen the efficacy of WRN inhibitors to additional cancer types." (PMID 38587317, 2024).
cancer (continued). "Similar approach has been employed to knock down the expression of the human Werner syndrome RecQ like helicase (WRN) in cancer cell lines, resulting in severe inhibition of cell survival." (PMID 38862431, 2024). "Subsequent work has revealed a broader role for WRN in many cancers and uncovered therapeutically useful synthetic interactions." (PMID 38994931, 2024). "Together, our data show that a degrader approach is a potentially powerful way of targeting WRN in MSI cancers and paves the way for the development of WRN-specific PROTAC compounds." (PMID 39242638, 2024). "Currently, there are at least two compounds, VVD-21437 and HRO76138 that are in early-stage clinical trials for WRN inhibition in MSI + cancers, and it remains to be seen how effective and well tolerated they are in patient populations." (PMID 39242638, 2024). "For example, cancer cells with high levels of microsatellite instability (MSI-H) are dependent on the Werner (WRN) helicase for survival." (PMID 39025847, 2024). "The identification of WRN as a synthetic lethal target in MSI-H cancers has opened new avenues for therapeutic intervention of these malignancies." (PMID 39025847, 2024). "Several large-scale functional genomics screens, including project DRIVE with 390 cell lines from the Cancer Cell Line Encyclopedia, have identified WRN as a synthetic lethal target in MSI cells." (PMID 38658754, 2024). "Here, the authors use a super-resolution optical platform and single molecule tracking to gain insight into WRN regulation in cancer." (PMID 39025847, 2024). "Specifically, RECQ helicases, including BLM, WRN, and RECQL4, are associated with various hereditary disorders characterized by cancer." (PMID 37415147, 2023). "Biallelic mutations in these RecQ homologs, WRN, BLM, and RECQL4, have been previously reported to be associated with rare human genetic diseases characterized by chromosomal instability and cancer susceptibility." (PMID 37180972, 2023). "Genome-wide screening studies have reported that WRN inhibition induces massive chromosome disruption and synthetic lethality in cancer cells with high MSI." (PMID 37130431, 2023). "WRN is also required for DNA damage repair and the survival of cancer cells with microsatellite instability (MSI)." (PMID 37130431, 2023). "The aberrant DNA hypermethylation is frequently detected in cancer cells which resulted in silencing the expression of certain genes such as Werner (WRN), a gene coding for a DNA helicase that helps in maintaining genomic integrity." (PMID 37092854, 2023). "Of the five different proteins in humans, RECQL1, BLM, WRN, RECL4, and RECQL5, three are associated with germline alterations associated with an increased risk of cancer." (PMID 35782872, 2022). "Biallelic, loss-of-function germline pathogenic variants in three of them, BLM, WRN, and RECQL4, have been linked to rare cancer-predisposing syndromes." (PMID 35782872, 2022). "We also demonstrated that inhibition of NF‐κB, with Ro106‐9920, enhanced the chemosensitivity of WRN‐WT cells while the effect was marginal in WRN‐KO cancer cells." (PMID 35582959, 2022). "Strikingly, biallelic mutations in 3 of 5 of these RecQ homologs — WRN, BLM, and RECQL4 — have been associated with rare genetic disorders in humans, characterized by chromosomal instability and cancer predisposition." (PMID 35025765, 2022). "Altogether, these results showed a novel role of WRN in triggering intrinsic/de novo resistance in cancers toward CPT to TOP1 inhibition through regulation of NF‐κB activation." (PMID 35582959, 2022).